KAT6B (lysine acetyltransferase 6B)
Diseases named in the same sentence as KAT6B in open-access papers (continued):
Sharing a sentence is not in itself a finding about the gene and the disease.
infection (5 papers, 2017 to 2023). The state of being infected such as from the introduction of a foreign agent such as serum, vaccine, antigenic substance or organism. "Of the genes participating in metal ion binding (MIB1, KAT6B, ITGA8, HBAC, KCNC1, and F13A), most were downregulated during the later stages of GCRV infection, whereas genes involved in protein ubiquitination (HERC1 and HERC4) were upregulated during the later stages of infection." (PMID 28906455, 2017).
neurodevelopmental disorder (5 papers, 2017 to 2026). A behavioral and cognitive disorder with onset during the developmental period that involves impaired or aberrant development of intellectual, motor, or social functions. "Heterozygous mutations in the histone lysine acetyltransferase gene KAT6B (MYST4/MORF/QKF) underlie neurodevelopmental disorders, but the mechanistic roles of KAT6B remain poorly understood." (PMID 39537341, 2025).
KAT6B also shares sentences with these, for which no sentence is quoted: myelodysplastic syndrome (4 papers); genetic disorders (3); intellectual disability syndrome (2); liver cancer (2); Angelman syndrome (1); Arboleda-Tham Syndrome (1); bladder cancer (1); Bohring-Opitz syndrome (1); Chiari malformation (1); cognitive disorder (1); colorectal cancer (1); congenital hydrocephalus (1); EARS disease (1); endometrial cancer (1); endometrial stromal sarcoma (1); Floating-Harbor syndrome (1); gynecological cancer (1); hematological malignancies (1); hepatocellular carcinoma (1); Kleefstra syndrome (1); Kyphosis (1); Laryngomalacia (1); lung carcinoma (1); medulloblastoma (1); memory impairment (1); mesenchymal neoplasms (1); microcephaly (1); neuroblastoma (1); neurological diseases (1); oligodendroglioma (1).
A further 6 diseases each share a sentence with KAT6B in 1 paper.